WDR41 (WD repeat domain 41)
Description:
Non-catalytic component of the C9orf72-SMCR8 complex, a complex that has guanine nucleotide exchange factor (GEF) activity and regulates autophagy. The C9orf72-SMCR8 complex promotes the exchange of GDP to GTP, converting inactive GDP-bound RAB8A and RAB39B into their active GTP-bound form, thereby promoting autophagosome maturation. As part of the C9orf72-SMCR8 complex, stimulates RAB8A and RAB11A GTPase activity in vitro, however WDR42 is shown not be an essential complex component for this function. The C9orf72-SMCR8 complex also acts as a negative regulator of autophagy initiation by interacting with the ULK1/ATG1 kinase complex and inhibiting its protein kinase activity.
Synonyms: MSTP048; FLJ10904
Tractability: Small molecule: a structure with a bound ligand is known. PROTAC: ubiquitination databases record sites on it; its protein half-life has been measured.
Gene: Protein-coding gene on chromosome 5 (77,425,970 to 77,620,611, reverse strand). Ensembl gene ENSG00000164253.
Subcellular location: Cytoplasm
Subcellular location (Human Protein Atlas): Nucleoplasm; Cytosol; Golgi apparatus
Gene Ontology:
Molecular function: GTPase activator activity; guanyl-nucleotide exchange factor activity; protein binding
Biological process: regulation of autophagy; negative regulation of exocytosis; negative regulation of immune response
Cellular component: cytoplasm; guanyl-nucleotide exchange factor complex; lysosomal membrane
Genetic constraint (gnomAD): Loss-of-function variants: 45 observed, 55.22 expected, observed/expected ratio (o/e) 0.81, 90% interval 0.64 to 1.04. The upper end of that interval is the gene's LOEUF score, 1.04, which puts it in group 4 of 6, group 1 being the genes least tolerant of losing a copy. Missense variants: 462 observed, 466.71 expected, observed/expected ratio (o/e) 0.99, 90% interval 0.92 to 1.07. Synonymous variants: 155 observed, 173.1 expected, observed/expected ratio (o/e) 0.9, 90% interval 0.79 to 1.02.
Homologues: Orthologues: chimpanzee WDR41 (99% identical), macaque WDR41 (94% identical), dog WDR41 (90% identical), guinea pig WDR41 (90% identical), rat Wdr41 (86% identical), mouse Wdr41 (85% identical), tropical clawed frog wdr41 (63% identical), zebrafish wdr41 (55% identical).
Diseases named in the same sentence as WDR41 in open-access papers:
WDR41 is named in the same sentence as 16 diseases in open-access papers, as found by Europe PMC text mining. Sharing a sentence is not in itself a finding about the gene and the disease. The quoted sentences say what the papers report.
Smith-Magenis syndrome (7 papers, 2017 to 2025). Smith-Magenis syndrome (SMS) is a complex genetic disorder characterized by variable intellectual deficit, sleep disturbance, craniofacial and skeletal anomalies, psychiatric disorders, and speech and motor delay. "The C9orf72 gene product forms a complex with SMCR8 (Smith-Magenis Syndrome Chromosome Region, Candidate 8) and WDR41 (WD Repeat domain 41) proteins." (PMID 32678027, 2020). "A series of studies have shown that the long isoform of human C9orf72 protein forms a complex with SMCR8 (Smith-Magenis Syndrome Chromosome Region, Candidate 8) and WDR41 (WD Repeat domain 41) proteins." (PMID 32678027, 2020). "In another example, Smith-Magenis Syndrome Chromosomal Region Candidate Gene 8 (SMCR8) forms the heterotrimer C9orf72-SMCR8-WDR41 complex (3 protein members in CORUM) together with the C9orf72-SMCR8 Complex Subunit (C9orf72) and WD Repeat Domain 41 (WDR41)." (PMID 36356032, 2022).
frontotemporal dementia (2 papers, 2021 to 2025). Frontotemporal dementia (FTD) comprises a group of neurodegenerative disorders, characterized by progressive changes in behavior, executive dysfunction and language impairment, as a result of degeneration of the medial prefrontal and frontoinsular cortices. "The best-predicted contact pair among the 19,141 in these data was between enhancer ENSR00000186261 and WDR41 (true value = 1.0, prediction = 0.99, E = 1.80 × 10−4), a protein-coding gene implicated in frontotemporal dementia and amyotrophic lateral sclerosis." (PMID 40180945, 2025).
breast carcinoma (1 paper, 2020). "First, we determined the protein level of WDR41 in breast cancer cells using 5‐aza‐dC, an inhibitor of DNA methylation, to verify our assumption." (PMID 32394588, 2020). "Here, we selected a variety of breast cell lines to investigate the expression of WDR41 and demonstrate the relationship between promoter methylation of WDR41 and breast cancer development." (PMID 32394588, 2020). "Taken together, these findings demonstrate that WDR41 expression is decreased in human breast cancer cells and breast cancer specimens." (PMID 32394588, 2020). "Based on a previous study on the role of WD‐repeat proteins in tumorigenesis, we first examined the expression pattern of WDR41 in breast cancer cell lines." (PMID 32394588, 2020). "Moreover, our results showed that aberrant methylation of WDR41 contributed to the proliferation, migration and survival of breast cancer cells via the AKT/glycogen synthase kinase‐3 beta (GSK‐3β)/β‐catenin signalling pathway." (PMID 32394588, 2020). "To ascertain the direct relationship between WDR41 expression and breast cancer, we evaluated the expression of WDR41 in human breast cancer chips, which contained 61 clinical stage samples, as well as the status of breast tumour tissues using immunohistochemical staining." (PMID 32394588, 2020). "Furthermore, a negative correlation was detected between the WDR41 level and the pathological grade of breast cancer patients and between WDR41 and TNBC." (PMID 32394588, 2020). "The present study was aimed to explore the role of WDR41 in breast cancer." (PMID 32394588, 2020). "After assessing the protein level of WDR41 in 14 pairs of human breast cancer tissues and their corresponding normal breast tissues, we found that WDR41 level was reduced in approximately 78.6% (11/14) of the tumour samples compared to that in paired normal breast tissue samples." (PMID 32394588, 2020). "Owing to WDR41 hypermethylation in leukoaraiosis, observed through DNA methylation chip (unpublished data), we hypothesized that WDR41 expression was potentially governed by DNA methylation in breast cancer as well." (PMID 32394588, 2020). "To determine the correlation between WDR41 levels and TNBC in human specimens, we further analysed the expression of ER, PR and Her2 in the human breast cancer specimens." (PMID 32394588, 2020). "Given the down‐regulated expression of WDR41 in breast cancer cells, we analysed its expression pattern in human breast cancer samples (grades II and III) to explore the relationship between WDR41 and breast cancer development." (PMID 32394588, 2020). "Moreover, we determined the mRNA levels of WDR41 in normal mammary epithelial cells (MCF‐10A) and breast cancer cells (MCF‐7, MDA‐MB‐231 and SKBR3 cells)." (PMID 32394588, 2020). "Combined with Western blotting and immunohistochemistry, the results showed that WDR41 was expressed at low levels in breast cancer, especially in triple‐negative breast cancer (TNBC)." (PMID 32394588, 2020). "Methylation inhibitor 5‐aza‐2′‐deoxycytidine (5‐aza‐dC) management increased the expression of WDR41 in MDA‐MB‐231 cells, but not in MCF‐10A (normal mammary epithelial cells) or oestrogen receptor‐positive MCF‐7 breast cancer cells." (PMID 32394588, 2020).
Leukoencephalopathy (1 paper, 2024). This term describes abnormality of the white matter of the cerebrum resulting from damage to the myelin sheaths of nerve cells. "In our analyses, TREM2, TYROBP, and GRN associated with leukoencephalopathy and FTD, show correlated gene expression, however, SMCR8 and WDR41, known to form a complex with C9orf72, did not." (PMID 38469573, 2024).
motor neuron disease (1 paper, 2020). "Finally, a recent RNA-Seq study comparing C9 FTLD and FTLD/motor neuron disease patients with unaffected control individuals reported a highly significant decrease in C9orf72 RNA levels in C9 FTLD samples; however, this data showed no significant change in SMCR8 or WDR41 RNA expression." (PMID 32678027, 2020).
triple-negative breast carcinoma (1 paper, 2024). An invasive breast carcinoma which is negative for expression of estrogen receptor (ER), progesterone receptor (PR), and human epidermal growth factor receptor 2 (HER2). "For instance, WD repeat protein 41 (WDR41) is under-expressed in triple-negative breast cancer, and methylated WDR41 positively regulates the AKT/GSK-3β/β-catenin pathway, promoting tumor proliferation, migration, and invasion." (PMID 39044262, 2024).
tumor (3 papers, 2020 to 2024). "Based on the apoptosis promotion function of WDR41 in vitro, we evaluated the levels of the apoptotic marker cleaved caspase 3 in tumours." (PMID 32394588, 2020). "Immunohistochemical staining results showed a higher expression of WDR41 in para‐carcinoma tissues than in paired tumour tissues." (PMID 32394588, 2020). "WDR41‐down‐regulation promoted, while WDR41‐up‐regulation inhibited the tumour characteristics of TNBC cells including cell viability, cell cycle and migration." (PMID 32394588, 2020). "In the present study, we demonstrated that the expression of WDR41 was lower in the TNBC cell lines than that in the tumour cell lines with low invasive capability (MCF‐7) or normal breast cell line (MCF‐10A)." (PMID 32394588, 2020). "However, patients with advanced grade (grade 2: G2 and grade 3: G3) always showed low WDR41 expression compared to patients with early grade tumours (G1) (P = .0002)." (PMID 32394588, 2020). "Aberrant methylation of WDR41 in MDA‐MB‐231 cells indicated that it might have acted as a tumour suppressor gene in the progression of TNBC." (PMID 32394588, 2020). "Further, WDR41‐up‐regulation dramatically suppressed tumour growth in vivo." (PMID 32394588, 2020). "Additionally, compared to that in the control group, tumour weight in the WDR41‐overexpressing group was markedly reduced by approximately 33% (P = .0462)." (PMID 32394588, 2020). "In the subnetwork related to tumor progression, the hubs from the blue module are the most connected, such as the genes Cmas, Kmt2a, Golt1b, Cdc34, Manf, Sco1, and Thoc3, followed by hubs from the light cyan (Extl2, Commd3, Wdr41, Keap1, Osbpl9) and pink modules." (PMID 32831131, 2020). "Further, WDR41 demethylation or up‐regulation suppressed the proliferative, migratory and tumour formation abilities of MDA‐MB‐231 cells by negatively regulating the AKT/GSK‐3β/β‐catenin signalling pathway, and this effect was attenuated by knockdown of WDR41." (PMID 32394588, 2020). "Here, our findings demonstrated that WDR41 affected the tumorigenesis of TNBC cells by regulating cell proliferation, migration, apoptosis and tumour growth in vivo and that WDR41 may act as a tumour suppressor of TNBC cells." (PMID 32394588, 2020).
WDR41 also shares sentences with these, for which no sentence is quoted: amyotrophic lateral sclerosis 1 (2 papers); Alzheimer disease (1); breast tumour (1); carcinoma (1); leukoaraiosis (1); lymph node metastasis (1); neurodegenerative disease (1); neurological disorders (1); psychiatric disorder (1).